ENSG00000267561 (novel protein)
Gene: Protein-coding gene on chromosome 1 (86,993,009 to 87,169,204, forward strand). Ensembl gene ENSG00000267561.
Genetic constraint (gnomAD): Loss-of-function variants: 11 observed, 22.24 expected, observed/expected ratio (o/e) 0.49, 90% interval 0.31 to 0.82. Missense variants: 211 observed, 271.36 expected, observed/expected ratio (o/e) 0.78, 90% interval 0.69 to 0.87. Synonymous variants: 73 observed, 92.28 expected, observed/expected ratio (o/e) 0.79, 90% interval 0.65 to 0.96.